LEP (leptin)
Diseases named in the same sentence as LEP in open-access papers (continued):
Sharing a sentence is not in itself a finding about the gene and the disease.
breast cancer (continued). "Leptin contributes to breast carcinogenesis through the increase of peripheral estrogen levels (directly or through upregulation of aromatase) and a positive association between serum leptin and estradiol has been found in pre- and post-menopausal women with breast cancer." (PMID 36077676, 2022). "In addition, there are studies that suggest that leptin (a hormone produced by adipocytes) is involved in increasing breast cancer risk in postmenopausal women, and targeting it might be a key to controlling cancer in such patients." (PMID 35294447, 2022). "Indeed, previous studies showed that activation of the leptin/ObR axis can result in a chronic inflammatory status, a well-known risk factor for breast cancer, with leptin being involved in CD4+ T-regulatory cells differentiation due to ObR overexpression on lymphocyte plasm membrane." (PMID 33644151, 2021). "Leptin and its OBRb receptor have been found to be overexpressed in breast tumors and high serum or intratumoral levels of leptin have been associated with a poor prognosis in breast cancer, indicating an important role for this adipokine in breast tumor progression." (PMID 33763424, 2021). "Additionally, IL-6 and leptin produced by adipocytes are known to promote angiogenesis, invasion, and metastasis, and we have previously shown that intratumoral angiogenesis is associated with metastatic recurrence in breast cancer." (PMID 34071012, 2021). "Therefore, there might be a correlation between serum leptin levels, leptin, and Ob-R expression in breast cancer patients which correspond with increased cancer risk, although there are currently no definitive data on this topic." (PMID 34210055, 2021). "While leptin, the prototype adipokine, was increased in patients with breast malignancies and was positively associated with disease progression in vitro, serum adiponectin, a beneficial adipokine, was lower in breast cancer patients and induced apoptosis and cell death in breast cancer cell lines." (PMID 33688343, 2021). "Furthermore, we aimed to verify whether similar estimates of association of adiponectin and leptin levels with breast cancer could be obtained with both methods." (PMID 34209441, 2021). "However, the association between leptin and Treg cells in breast carcinoma remains unexplored." (PMID 34868066, 2021). "Both elevated leptin and resistin concentrations was associated with the promotion of cancer stem cell survival and the promotion of invasion and migration via epithelial to mesenchymal transition in breast cancer cells, which contributes to the development of treatment resistance." (PMID 32257945, 2020). "Our findings thus support the previous observations on the association of excessive leptin in breast cancer progression and reveal a novel, co-operative action of the leptin receptor and mechanosensitive Ca2+ channels, which could favor the development of invasive breast cancer." (PMID 33490070, 2020). "Thus, leptin-ObR-CXCR4 interplay may add another layer of complexity to the mechanisms underlying the deleterious effects of the breast cancer microenvironment in the resistant setting." (PMID 32260113, 2020). "In addition to its direct action through its own receptor, leptin can crosstalk with other different signaling molecules, including ERα, growth factors, Notch, and inflammatory cytokines to further affect breast cancer risk, progression, recurrence and mortality." (PMID 30634494, 2019). "Additionally, leptin has been considered as a mediator of tumor-stromal interactions, where it seems to participate in the crosstalk between breast cancer cells and tumor-associated macrophages M2 by stimulating IL-18 and IL-8 production to promote tumor growth and metastasis." (PMID 31380268, 2019).
breast cancer (continued). "Remarkably, weight loss interventions through diet and exercise in overweight/obese breast cancer survivors were associated with a decrease in specific biologic factors related to breast cancer recurrence and mortality, such as estrogen, insulin, and leptin levels." (PMID 30634494, 2019). "However, not only the overexpression of leptin and its receptor favors tumor progression, but also polymorphisms (variation in specific DNA sequences) of leptin or its receptor genes are considered potential mechanisms of enhanced susceptibility to develop breast cancer." (PMID 30404206, 2018). "Adiponectin and leptin are two adipokines that may act oppositely on the risk of breast cancer." (PMID 27936468, 2017). "Moreover, further large-scale multicenter studies with more detailed individual data, with different environmental background are warranted to further validated gene–gene and gene–environment interactions on Leptin-2548G/A gene polymorphism and breast cancer risk." (PMID 26825898, 2016). "Leptin being a pleiotropic adipokine has been shown to cause activation of various signaling pathways leading to tumor growth/cell proliferation, such as via up regulation of angiogenesis in breast cancer, or suppression of apoptosis in colon cancer cells, and hepatic cancer cells." (PMID 25704884, 2015). "Specifically MMTV-TGF-α mice crossed with leptin deficient mice fail to develop tumors and treatment with a leptin antagonist decreases the growth of murine triple-negative breast tumors and 4T1 mammary cancer cell growth via reducing levels of VEGF, pSTAT3 and cyclin D1." (PMID 25360510, 2014). "Indeed, estrogen receptor (ER) α and ObRs are coexpressed in malignant mammary tissue and breast cancer cell lines and it has been shown a positive association between serum leptin levels and elevated values of estrogen and progesterone receptor in patients with breast cancer." (PMID 25505738, 2014). "Therefore, leptin level is proposed as a screening tool in groups with high breast cancer risk." (PMID 23826274, 2013). "Interestingly, leptin pro-angiogenic signature in breast cancer was found linked to IL-1 signaling." (PMID 21731759, 2011). "Therefore, leptin pro-angiogenic actions in breast cancer may be linked to, or regulated in part by IL-1 signalling." (PMID 21139583, 2011). "In addition, conditional logistic regression, which preserves the matching of cases and controls, was used to estimate odds ratios (ORs) and 95% confidence intervals (CIs) for the associations between plasma leptin levels and anthropometric measures and breast cancer risk." (PMID 19223908, 2009). "Consistent with these cellular findings, EMT scores derived from data on breast cancer patients exhibited a robust positive correlation with LEP and LEPR expression levels (p < 0.0001)." (PMID 41562922, 2026). "Among these adipokines, leptin stands out as a central player in promoting breast cancer progression, contributing to key tumorigenic processes, including cell growth, survival, migration, and invasion." (PMID 40485730, 2025). "In conclusion, LEP promotes breast cancer progression through multiple mechanisms; however, certain aspects, such as how its interaction with immune cells influences tumor development, remain not fully elucidated." (PMID 41269404, 2025). "miR-204-5p, derived from breast cancer, induces the production of leptin by cancer-related adipocytes." (PMID 40076482, 2025). "This is supported by two RCTs conducted in breast cancer survivors, which demonstrated that combined caloric restriction and exercise interventions yielded greater improvements in glucose, leptin, and CRP levels than caloric restriction alone." (PMID 40895542, 2025). "It has been reported that leptin levels are increased in the plasma of patients with breast cancer, which correlates with higher grade, advanced tumor stages, and aggressive subtypes." (PMID 41353220, 2025).
breast cancer (continued). "Earlier studies also reported increased adiponectin/leptin ratio in serum and plasma with CR and their role in breast cancer incidence." (PMID 40986521, 2025). "Leptin significantly upregulated the mRNA expression of MTA1 in both breast cancer cell lines, indicating regulation at the transcriptional level." (PMID 40565190, 2025). "Among these leptin antagonists, only LPrA2 has been certified as effective in the decrease of leptin-induced effects in breast cancer patients with multidrug resistance to sunitinib, doxorubicin, cisplatin, and paclitaxel." (PMID 40227577, 2025). "This study provides a comprehensive and in-depth understanding of the pivotal role of leptin-rich extracellular vesicles derived from obese adipose tissue (OB EVs) in enhancing breast cancer malignancy." (PMID 40485730, 2025). "Prior studies demonstrated that leptin stimulates the growth of human breast cancer cells in vitro and promotes angiogenesis via vascular endothelial growth factor (VEGF) and VEGF receptor 2 (VEGF2) pathways." (PMID 40986521, 2025). "Adipocytes and ASCs act as the local sources of leptin and adiponectin, with a high leptin‐to‐adiponectin ratio being reported within breast cancer TME." (PMID 39496581, 2025). "The qPCR and Western blot analysis revealed a positive correlation between MTA1 expression and leptin treatment in both breast cancer cell lines." (PMID 40565190, 2025). "Elevated plasma levels of leptin and IL-6 were noted in a postmenopausal obesity tumor-bearing mouse model of breast cancer." (PMID 40303301, 2025). "Conversely, the median serum level of leptin in breast cancer cases was significantly higher than that in controls." (PMID 40902078, 2025). "Overall, our results highlight how obese adipose tissue modulates breast cancer cell behavior, with leptin-enriched EVs playing a central role in driving migration, metabolic reprogramming, and invasiveness, thereby promoting tumor malignancy." (PMID 40485730, 2025). "Release of the exosomal miR‐204‐5p by breast cancer cells has been recently reported to induce leptin signaling, promoting WAT lipolysis and browning in cancer‐associated cachexia." (PMID 39496581, 2025). "Below, we will examine the relationships of two prominent adipokines—adiponectin and leptin—with breast cancer." (PMID 41269404, 2025). "This study investigated the role of MTA1 in the relationship between leptin and VM in human breast cancer cells." (PMID 40565190, 2025). "Collectively, these results highlight the critical role of the leptin derived from the obese AT within EVs in driving the increased malignancy of breast cancer cells." (PMID 40485730, 2025). "Leptin behaves as a growth factor in breast cancer, activating multiple oncogenic signaling pathways and improving estrogen synthesis in adipose stromal cells." (PMID 41463076, 2025). "The leptin/Ob-R/STAT3 signaling axis plays a critical role in breast cancer development by regulating target genes involved in tumor growth and progression." (PMID 40565190, 2025). "Beyond their involvement in breast cancer progression, leptin and adiponectin plays a central role in metabolism, regulating appetite, energy balance, and adipose tissue function." (PMID 40986521, 2025). "Polymorphisms in the LEP and LEPR genes are associated with an increased risk of breast cancer and more aggressive disease progression." (PMID 41269404, 2025). "Leptin has been shown to modulate tumor cell behavior, contributing to an aggressive phenotype in breast cancer." (PMID 40565190, 2025). "Among biomarkers related to glucose metabolism, leptin showed the most substantial and statistically significant improvement, aligning with findings from studies focused on breast cancer survivors." (PMID 40895542, 2025). "Leptin acts on multiple cell types of healthy mammary tissue and breast cancer, including on mammary-resident (and tumor-resident) macrophages, which can contribute to tumor neovascularization." (PMID 39439572, 2024).
breast cancer (continued). "Leptin plays a vital role in the development and progression of breast cancer by activating STAT3 signaling." (PMID 38791252, 2024). "In in vitro models of breast cancer, the role of leptin on proliferation, migration, epithelial-mesenchymal transition (EMT), and cell invasion by activating signaling pathways such as ERK, STAT3, and FAK-Src has been described." (PMID 38228661, 2024). "Adipose tissue is the source for key adipokines such as adiponectin and leptin and the ratio of adiponectin/leptin is adversely affected in obese breast cancer patients." (PMID 39253073, 2024). "Leptin-induced pro-inflammatory signaling and immune cell activation can indirectly enhance angiogenic responses in breast cancer and other tissues through several mechanisms." (PMID 39439572, 2024). "In particular, components such as IL6 and leptin have been demonstrated to play a significant role in resistance to treatments like Tamoxifen and Paclitaxel in breast cancer patients." (PMID 39767718, 2024). "Taken together, our data suggest that leptin differentially influences tumor characteristics of breast cancer cells." (PMID 38228661, 2024). "This same study also showed upregulation of leptin in serum of breast cancer patients in comparison to the healthy individuals." (PMID 39439572, 2024). "Leptin is also involved in regulating immune responses, reproduction, and proliferation of many cell types, including breast cancer cells." (PMID 39609706, 2024). "Leptin is also secreted by cancer cells, and its overexpression is particularly observed in breast cancer cells." (PMID 38791252, 2024). "For example, leptin will not only promote TAMs through NF-κB/nuclear factor-κB1 (NF-κB1) but also the expression and secretion of interleukin-18 (IL-18) in breast cancer cells through the PI3K/AKT/ATF2 pathway." (PMID 38672455, 2024). "Leptin, for instance, promotes the growth of breast cancer cells, tumor angiogenesis, and inhibits apoptosis, whereas adiponectin exhibits opposing effects by reducing tumor cell proliferation and angiogenesis, thus restricting nutrient supply to tumors." (PMID 39346906, 2024). "Overall, we suggest that the biological effect of leptin on hormone receptor-positive breast cancer cell proliferation is mediated by autophagy." (PMID 38228661, 2024). "Leptin, an energy balance regulator secreted by adipocytes, increases metastatic potential of breast cancer cells." (PMID 39609706, 2024). "Given the critical role that angiogenesis plays in cancer development and patient survival outcomes, the role of leptin in driving angiogenesis in obese breast cancer patients is of critical relevance." (PMID 39439572, 2024). "Leptin signals directly to breast cancer stromal cells by paracrine and/or autocrine signaling activation of cell surface leptin receptors (LEPRs), ObR-a and ObR-b." (PMID 39439572, 2024). "Given the known role of adipose tissue in cancer initiation and progression, and considering that adiponectin was a risk biomarker for breast cancer in the same cohort, we assessed the relationship between PCSK9 and the adipokines adiponectin and leptin." (PMID 38611089, 2024). "This is consistent with previous research that indicates direct inactivation of ACC by leptin leads to invasion of breast cancer cells." (PMID 39609706, 2024). "In ER+ breast cancer cells, leptin increases aromatase expression and enzymatic activity, leading to an increase in overall estrogen levels." (PMID 39439572, 2024). "Elevated leptin expression in breast cancer is indicative of a more aggressive cancer phenotype and is associated with tumor size, lymph node involvement, and metastasis." (PMID 38255203, 2024). "The impact of leptin on migration in 5 mM glucose medium was assessed in murine triple negative metastatic 4T1 and metM-Wntlung breast cancer cell lines." (PMID 39609706, 2024). "Separately, leptin was found to regulate breast cancer cell growth in a Wnt/β-Catenin-mediated manner." (PMID 39439572, 2024).
breast cancer (continued). "Leptin derived from adipocytes also promotes Plasminogen activator inhibitor-1 (PAI-1)-mediated breast cancer metastasis in a STAT3/miR-34a-dependent manner." (PMID 38672455, 2024). "Previous studies have shown that adipokines such as adiponectin can induce cell apoptosis and enhance the effects of DOX in breast cancer while leptin and resistin can decrease cancer cell apoptosis and reduce the efficacy of DOX." (PMID 38238320, 2024). "STAT3 is a transcription factor that affects breast cancer progression and chemoresistance by regulating several oncogenes and participates in the leptin/Ob-R signaling pathway." (PMID 38791252, 2024). "To demonstrate the involvement of autophagy in some of the leptin-induced cancer characteristics, we first determined the effect of leptin on autophagy in breast cancer cells." (PMID 38228661, 2024). "We then analyzed the correlation between the combinational effect of blood adiponectin and leptin with recurrence, as reported in a study in which the A/L ratio was decreased in women with breast cancer and in a mouse model of TRAMP." (PMID 39201655, 2024). "Using two murine models of metastatic triple-negative breast cancer (TNBC) differing in their genetic alterations, we investigated the impact of leptin signaling on breast cancer metastasis under physiological (5 mM) glucose conditions." (PMID 39609706, 2024). "We observed that leptin treatment significantly increased maximal respiration and mitochondrial spare respiratory capacity in all breast cancer cell lines (yellow bar)." (PMID 38228661, 2024). "Our study is the first to investigate the impact of leptin on metastatic breast cancer cell migration maintained in a physiological level of glucose." (PMID 39609706, 2024). "Leptin is involved in the proliferation, survival, angiogenesis, and metastasis of breast cancer cells and plays an important role in the development of breast cancer in obese postmenopausal women." (PMID 38791252, 2024). "The results of the current study demonstrate increased migratory capability of breast cancer cells following leptin treatment in physiological glucose conditions, an interesting result not reported previously." (PMID 39609706, 2024). "Several studies have highlighted the importance of the ratio of two adipokines, leptin, and adiponectin, to the progression of postmenopausal breast cancer as well as TNBC." (PMID 38888911, 2024). "Before analyzing mitochondrial function, breast cancer cells were treated with leptin and/or CQ for 24 h." (PMID 38228661, 2024). "In a previous work, we demonstrated that autophagy participates in leptin-induced migration in breast cancer cells." (PMID 38228661, 2024). "Leptin promotes breast cancer cell proliferation by activating STAT3; in this process, SRC-1 can be recruited to the STAT3 promoter and interact with its activation domain to enhance STAT3 signalling." (PMID 38553750, 2024). "Previous reports in breast cancer cells suggest that autophagy is required to sustain leptin-driven Extracellular-Signal-Regulated-Kinase phosphorylation (ERK), cellular proliferation and migration." (PMID 38228661, 2024). "This study aimed to investigate the relationship between leptin and VM in human breast cancer cells." (PMID 38791252, 2024). "In conclusion, leptin-induced autophagy supports mitochondrial metabolism in breast cancer cells as well as glycolysis in triple negative cells." (PMID 38228661, 2024). "In a study of women undergoing mastectomy or breast cancer surgery, CLS was detected in 40% of cases, and was associated with higher levels of insulin, glucose, leptin, triglycerides, C-reactive protein and IL-6." (PMID 39251829, 2024). "The secretion of adipokines, including adiponectin and leptin, influences breast cancer cell proliferation and invasion." (PMID 38473978, 2024).